NF1 (neurofibromin 1)
Diseases named in the same sentence as NF1 in open-access papers (continued):
Sharing a sentence is not in itself a finding about the gene and the disease.
breast cancer (continued). "Tumor predisposition has long been associated with NF1, and an increased breast cancer (BC) incidence and reduced survival have been reported in recent years for women with NF1." (PMID 38270845, 2024). "Patients with a pathologic variant of NF1 should be followed carefully, because they are at a high risk of developing gastrointestinal tumors, including NETs, not only breast cancer." (PMID 38282102, 2024). "Alternatively, upregulation of p21 expression is reported to induce autophagy and to drive the onset of mitophagy, as well as mitochondrial dysfunction, in NF1-deficienct breast cancer cells." (PMID 39016685, 2024). "To accurately model the germline monoallelic NF1 mutations in NF1 patients, we utilized an Nf1-deficient rat model with accelerated mammary development before presenting with highly penetrant breast cancer." (PMID 38799507, 2024). "This elevated risk has warranted the recommendation for earlier breast cancer screening at the age of 30 for women with NF1." (PMID 38799507, 2024). "The correlation between NF1 and the risk of developing breast cancer has become increasingly evident in recent years." (PMID 38270845, 2024). "Here we show for the first time that Nf1-deficiency impacts mammary stroma and the extracellular matrix, especially collagen formation, before mammary tumor formation." (PMID 38799507, 2024). "To address this question, we developed a rat model of Nf1-deficient breast cancer by creating several distinct germline Nf1 indels using CRISPR/Cas9 genome editing in immunocompetent Sprague Dawley rats." (PMID 38799507, 2024). "Patients with NF1 have a high risk of developing benign and malignant tumors, particularly breast cancer." (PMID 38282102, 2024). "NF1 loss of function is also more commonly detected in endocrine-resistant and metastatic breast cancer cases." (PMID 38799507, 2024). "In a molecular characterization study of ER+ MBC utilizing circulating tumor DNA (ctDNA), mutations in the NF1 gene were acquired in 8.1% of breast cancers exposed to endocrine therapy." (PMID 38003387, 2023). "Breast cancer patients with NF1 sporadic mutations treated with the estrogen-receptor antagonist fulvestrant showed a good outcome." (PMID 37081086, 2023). "As previously reported, patients who possess NF1 mutations or lose the expression of PTEN have worse survival in breast cancer." (PMID 36836424, 2023). "An NF1 mutation in breast cancer has been found to be associated with ER/PR negativity, HER2 amplification, and worse survival." (PMID 37173992, 2023). "NF1 is a tumor suppressor, which was observed to be inactivated through loss-of-function mutations in mouse mammary tumors and human BCs." (PMID 37094040, 2023). "NLGN1, specifically, was described as an oncogene shown to be upregulated in NF1-associated breast cancer." (PMID 37770931, 2023). "Population studies on breast cancer samples revealed a correlation between NF1 loss and upregulation of estrogen receptor (ER)-associated pathways in human breast cancer tissues, as well as increased ER activity in rat models of mammary adenocarcinoma." (PMID 35188187, 2022). "NF1 truncating mutations were identified as breast cancer driver alterations in both primary and metastatic lesions." (PMID 36358725, 2022). "NF1 was mutated in both the primary and recurrence for one breast and one ovarian cancer, and in two breast cancer recurrences." (PMID 36344544, 2022). "NF1-deficient HER2-positive breast cancer cell lines show resistance to the HER2 kinase inhibitors lapatinib, neratinib, and tucatinib." (PMID 36358725, 2022). "NF1 is one of the 12 breast cancer predisposition genes identified to date, however, virtually all previous studies have focused on evaluating breast cancer risk associated with putative pathogenic SNVs and small InDels." (PMID 35493102, 2022).
breast cancer (continued). "Mutation or deletion of NF1 in breast cancer is associated with increased ER phosphorylation, endocrine therapy-resistant breast cancer growth, and ultimately poorer clinical outcome." (PMID 35505937, 2022). "NF1 mutation or loss are common genetic events both in sporadic and NF1-associated breast cancer, where NF1 loss was associated with increased tumor aggressiveness and poor patient prognosis." (PMID 35188187, 2022). "Through Metascape, we found that genes grouped in the third cluster are target genes for the transcription factor NF1, a tumor suppressor gene that has been reported to be associated with an increase in breast cancer risk when lost." (PMID 36224576, 2022). "A report showed that NF1 deficiency correlated with estrogen receptor phosphorylation and poor survival in breast cancer." (PMID 34205170, 2021). "Previously, although the association between NF1 and cancers of the nervous system was clearly defined, the link between the disorder and breast cancer was just hinted at with only case reports to rely on." (PMID 33842116, 2021). "By using mouse models, scientists have confirmed the loss of Nf1 and their link to breast cancer tumorigenesis." (PMID 34566848, 2021). "Compared to healthy females, female NF1 patients have an estimated 2-fold increase in lifetime risk of breast cancer (18.0%)." (PMID 34566848, 2021). "NF1 patients have a five-fold increased risk of developing breast cancer, and individuals with sporadic breast cancer commonly have mutations in NF1." (PMID 33669386, 2021). "In malignant, sporadic non-NF1-associated tumors such as pheochromocytoma, lung adenocarcinoma, breast cancer, ovarian cancer, glioblastoma and many others, somatic pathogenic variants of NF1 are also important targets." (PMID 33863389, 2021). "This new model enables researchers to investigate the interplay between NF1 and estrogen receptor (ER) signaling in sporadic and NF1-associated breast cancer and underscores the importance of alternative animal models." (PMID 33669386, 2021). "NF1 has also been associated with an increased risk of breast cancer, with specific NF1 variants conferring a distinctive cancer risk." (PMID 33919865, 2021). "The link between NF1 and breast cancer is now well recognized, both biologically and clinically, with NF1 patients having greater risk, more adverse prognostic risk factors, and increased mortality for breast cancer." (PMID 33842116, 2021). "The oncosuppressor activity of NF1 has been later confirmed by the findings of somatic NF1 mutations in many human cancers, including breast cancer, ovarian cancer, lung cancer, glioblastoma and acute myeloid leukemia." (PMID 31979111, 2020). "Based on this increased risk of early-onset breast cancer in female patients with NF1, annual breast screening with mammography was recommended by expert opinion to begin at age 40 years." (PMID 32014052, 2020). "In ER+ breast cancer models, NF1 loss induced resistance to endocrine therapy through ER-dependent and ER-independent mechanisms." (PMID 32210163, 2020). "The finish stud y and a retrospective review (n = 76) in the United States respectively showed a two-fold and 2.8-fold increased risk of breast cancer in patients with NF1 over age 50 years." (PMID 32014052, 2020). "Under the appropriate conditions, the loss of NF1 can enhance the competitive growth advantages of breast cancer cells harboring NF1 mutations." (PMID 33061844, 2020). "Other recent studies focused on the identification of NF1 mutations in advanced breast cancers and in the definition of their potential role in the mechanisms of resistance to endocrine therapy." (PMID 32210163, 2020). "Treatment of NF1-associated breast cancer is similar to that of breast cancer in the general population." (PMID 32014052, 2020). "Women with NF1 who were 50 years of age and older demonstrated a smaller increased risk of breast cancer compared to women 50 years and older in the general population." (PMID 30962859, 2019).
breast cancer (continued). "That being said, our study cohort was small, and minimal information exists in the current literature concerning the role of breast cancer family history and breast cancer risk in female NF1." (PMID 31121919, 2019). "This suggests that women diagnosed with NF1 can be integrated into routinized breast screening programs, much like other women at high risk of breast cancer." (PMID 31121919, 2019). "Appropriate physician and patient education with increased awareness of the association of early onset breast cancer in patients with NF1 and the need for early breast cancer screening is crucial for this patient population." (PMID 30962859, 2019). "In the current study, we conducted a systematic review of the literature and meta-analysis of epidemiological studies to quantitatively assess the association between NF1 and the risk of breast cancer." (PMID 30962859, 2019). "Considering that a positive family history of breast cancer can significantly increase an individual’s lifetime risk, further investigations are needed in larger NF1 cohorts to examine the moderating effect of family history on NF1-related breast cancer risk." (PMID 31121919, 2019). "The increased risk of breast cancer in NF1 has now been reported by numerous groups, including a recent review of the literature which examined 32 published epidemiological studies focused on the potential association of NF1 and increased breast cancer risk." (PMID 31121919, 2019). "The strength of the association between NF1 and the increased breast cancer risk remains uncertain due to the small study populations and differences in participants and methodological methods used in the previous studies." (PMID 30962859, 2019). "Specifically, certain point mutations were shown to significantly increase the risk of breast cancer in female NF1 patients <50 years of age." (PMID 31121919, 2019). "The increased risk of breast cancer found in this meta-analysis and other previous studies reinforces that increased attention to the breast cancer risk in young women with NF1 is needed." (PMID 30962859, 2019). "Case reports and several cohort and epidemiological studies have described an association of breast cancer with NF1." (PMID 30962859, 2019). "The NF1 gene has been implicated as a breast cancer driver with somatic mutations reported in 27.7% of all breast carcinomas." (PMID 30962859, 2019). "Women with NF1 <50 years of age possess an up to five-fold increased risk of developing breast cancer compared with the general population." (PMID 31121919, 2019). "Studies suggest that women < 50 years old (y.o.)with NF1 have an increased breast cancer (BC) incidence and BC associated mortality." (PMID 30962859, 2019). "NF1 mutations have been known to associate with increased risk of breast cancer in younger population and poor breast cancer survival." (PMID 29566657, 2018). "Here, combining archival formalin-fixed paraffin embedded tissue and targeted sequencing in three cohorts of ER+ breast cancer, the authors find associations with clinical outcome for NF1 frame-shift nonsense mutations, PIK3R1 mutation, and DDR1 mutations." (PMID 30181556, 2018). "We also validated estrogen dependence of Nf1-deficient breast cancers by ablating mammary tumors in our Nf1 rat model by ovariectomy." (PMID 30182054, 2018). "The results demonstrate the impact of Nf1 loss of function on mammary tumor initiation in both male and female hormonal environments." (PMID 30182054, 2018). "A predisposition to breast cancer in NF1 patients has led researchers to postulate the potential involvement of somatic NF1 mutations in initiating and driving the malignant transformation and progression of sporadic breast cancer." (PMID 28637487, 2017). "The NF1 gene is reported to be frequently mutated in sporadic breast cancers, although in only a few studies has mutation frequency been published." (PMID 28637487, 2017).
breast cancer (continued). "NF1 patients have an increased risk of developing breast cancer as compared to the general population." (PMID 28637487, 2017). "In particular, women under the age of 50 with NF1 have an increased (4–5-fold) risk of developing breast cancer (standardized incidence ratio for women under 50) and also a 3.5-fold increased fatality risk (proportionate mortality ratio)." (PMID 28637487, 2017). "There were 29 cases of breast cancer in NF1 patients and six studies about the association between breast cancer and NF1." (PMID 26604930, 2015). "The first cases describing the association of NF1 with breast cancer were reported in the 1970s by Brasfield and Das Gupta." (PMID 25889501, 2015). "In conclusion, it is important that patients and physicians are aware of the increased risk of breast cancer in the NF1 subset." (PMID 25885768, 2015). "A previous article reported the development of breast cancer in a 21-year-old woman with NF1 and BRCA1 mutations." (PMID 26604930, 2015). "The first report of an association between NF1 and breast cancer was published in 1972, and subsequently several clinical cases of NF1 patients with breast cancer have been reported in the literature." (PMID 26604930, 2015). "Concluding that, although reported cases are rare, the association between breast cancer and NF1 is common and patients with NF1 have a moderately elevated risk of developing breast cancer." (PMID 25889501, 2015). "Even if the association between breast cancer and NF1 is rarely reported, the few studies found in the literature suggest that women with NF1 are at a higher risk of developing breast cancer when compared to the general population." (PMID 25889501, 2015). "Neurofibromatosis type 1 (NF1) is one of the most common genetic diseases in humans and is associated with various benign and malignant tumors, including breast cancer." (PMID 26604930, 2015). "Here, we report two cases of breast cancer in NF1 patients and review the literature on the association between NF1 and breast cancer." (PMID 26604930, 2015). "Other missense mutations were found in tumor suppressor genes, including the susceptibility gene for breast cancer BRCA2 (n = 6) or the RAS family negative regulator NF1 (n = 1)." (PMID 26155992, 2015). "The Cancer Genome Project led by the Sanger Institute and The Cancer Genome Atlas (TCGA) projects reported NF1 mutations in approximately 3% of the breast cancers sequenced." (PMID 25026295, 2014). "All these studies agree that women with NF1 are at higher risk for breast cancer than the general population, particularly when they are younger than 50 years old." (PMID 24876981, 2014). "In summary, since breast cancer has been associated in the literature with NF1, affected patients require screening for breast tumors." (PMID 24876981, 2014). "Our conclusions are that since NF1 is mutated or deleted in one third of sporadic breast cancers, its role as a molecular driver for treatment has to be further explored." (PMID 24565603, 2014). "The finding that both the NF1 gene and a breast cancer predisposition gene (BRCA1) are located in close proximity on chromosome 17q makes the association of these two conditions intriguing." (PMID 20205809, 2010). "Individuals with NF1 have an increased predisposition to several malignancies, particularly malignant peripheral nerve sheath tumors, and face a 5-fold higher risk of breast cancer compared with the general population." (PMID 41487701, 2026). "NF1 mutations are detected in only 2–5% early-stage ER+ breast cancers." (PMID 41226361, 2025).
breast cancer (continued). "Young women with NF1 (<50 years) have an up to five-fold increased risk of breast cancer." (PMID 38859614, 2025). "It is now known that NF1 gPVs may increase risk to develop breast cancer and there have been reports of thyroid cancer." (PMID 39979679, 2025). "Young women with NF1 are at a high risk of developing breast cancer." (PMID 38282102, 2024). "Thus, we have to consider two issues: what is the risk level of patients with NF1 and breast cancer for another de novo tumor, and how should we follow-up and treat patients with NF1 after mastectomy considering multiple neoplasms?" (PMID 38282102, 2024). "The risk of breast cancer in patients with NF1, particularly in young women, is very high." (PMID 38282102, 2024). "While there has been some suggestion that NF1 loss of function mutations are associated with greater HER2 expression in breast cancers, it is unclear whether the differing NF1 copy number in this tumor contributed to the difference in HER2 expression." (PMID 39069534, 2024). "Previous studies have shown that RNF213 co-mutates with NF1 in human breast cancer samples." (PMID 39338204, 2024). "In addition to identifying a role for Nf1 in promoting adipocyte plasticity, these findings also uncover important questions regarding Nf1 loss in breast cancer initiation." (PMID 38799507, 2024). "In addition, NF1 has been reported to be mutated more frequently in ER+ metastatic breast cancer, suggesting it is a driver of breast cancer progression." (PMID 37081086, 2023). "NF1 loss-of-function mutations are detectable in about 2% of primary ER+ breast tumors, but up to 20% of the primary ER+ breast cancer can be considered NF1-deficient because of an association with a poor response to adjuvant endocrine therapy at the mRNA level." (PMID 37501682, 2023). "However, the association of breast cancer risk with NF1 was only identified in NCCN, and RECQL was only identified in ClinGen." (PMID 33959510, 2021). "However, more recent studies have since established a strong clinical association between NF1 and breast cancer." (PMID 33842116, 2021). "To determine whether NF1 loss limits the efficacy of anti-HER2 therapy, we depleted NF1 expression in a panel of HER2 + breast cancer cell lines using either short hairpin (sh) RNAs or CRISPR/Cas9." (PMID 34795269, 2021). "It has been suggested that NF1 patients may be at higher risk of developing contralateral breast cancer." (PMID 33842116, 2021). "The NF1 gene is located on the long arm of chromosome 17, which also contains the BRCA1 gene, and some have suggested possible concomitance of NF1 and hereditary breast cancer, though few cases of breast cancer in patients with both NF1 and BRCA1 mutations have actually been reported." (PMID 33842116, 2021). "However, a recent study of more than 113,000 women was unable to definitively show an association between NF1 and breast cancer risk." (PMID 34771713, 2021). "The co-occurrence of NF1 and BRCA1/2 germline mutations may suggest a potential link to early-onset breast cancer in NF1 patients and calls for the study of more cases to obtain a convincing conclusion." (PMID 34566848, 2021).